TM4SF4 (transmembrane 4 L six family member 4)
Diseases named in the same sentence as TM4SF4 in open-access papers (continued):
Sharing a sentence is not in itself a finding about the gene and the disease.
tumor (12 papers, 2006 to 2026). "In CRC, higher TM4SF4 expression is associated with liver metastasis, worse survival, tumor development and epithelial-mesenchymal transition (EMT) program regulated by TGFβ/Snail, TNFα/NFκB, and thymidylate synthase pathways." (PMID 39999090, 2025). "According to the immunohistochemical survey of HCC tissue microarray, the expression level of TM4SF4 protein in HCC was linked to tumor progression, as higher expression occurred in the early stages of HCC." (PMID 36678607, 2023). "Given its pivotal role in tumor progression and therapy resistance, TM4SF4 represents a promising therapeutic target." (PMID 41356204, 2026). "Treatment with Hz2B7-1.2 in these cells reduced cellular TM4SF4 expression, indicating effective binding of the antibody to tumor cells." (PMID 41356204, 2026). "In a separate report, TM4SF4 protein was also overexpressed in HCCs compared with paired non-tumor tissues by utilizing an in-house anti-TM4SF4 polyclonal antibody." (PMID 39999090, 2025). "Inoculated mice were divided into two groups, one group in which anti-TM4SF4 antibody was injected peritumorally at six time points after tumor injection, and the control group, in which vehicle (phosphate-buffered saline [PBS]) was injected." (PMID 25344917, 2014). "Without antibody treatment, tumor burdens increased up to 2,500 mm3 49 days after injection of tumor cells; however tumor volume in the anti-TM4SF4 antibody-treated group was less than 100 mm3." (PMID 25344917, 2014). "These three tumor cell lines express substantial levels of TM4SF4." (PMID 41356204, 2026). "TM4SF4 highly expressed on the surface of HCC cells are not necessarily tumor-associated antigens due to lack of actual immunotherapeutic agent demonstrating potency against TM4SF4 in HCCs." (PMID 39999090, 2025). "In addition, the candidate genes SERPINB5 (P = 0.008) and TM4SF4 (P = 0.043), which were upregulated in the mesenchymal tumor cells, correlated with a significantly decreased survival potential in patients with higher expression levels." (PMID 28687755, 2017). "We examined next whether antibody-mediated inactivation of TM4SF4 suppresses tumor cell growth or the expression of growth factors." (PMID 25344917, 2014). "However, treatment of gamma-irradiated cells with anti-TM4SF4 antibody more severely decreased the tumor cell survival." (PMID 25344917, 2014). "It was also confirmed that TM4SF4 is involved in invasiveness of tumor cells." (PMID 25344917, 2014). "In addition, combination treatment of anti-TM4SF4 antibody and radiation was shown to be more effective in tumor removal." (PMID 25344917, 2014). "Suppression of TM4SF4 significantly inhibits HCC cell growth, underscoring its potential as a target for preventing tumor progression." (PMID 41356204, 2026). "Knockdown of TM4SF4 in HCC cells impaired growth potential in vitro and repressed tumor growth in a mouse xenograft model of human HCC, similar with another study showing attenuated proliferation and migration of TM4SF4-silenced HCC cells." (PMID 39999090, 2025). "Among them, TM4SF1, TM4SF4, and TM4SF5 are grouped under the transmembrane 4 L6 domain family, and they have been studied for their expression and roles in various tumor biological activities." (PMID 36678607, 2023). "Additionally, TM4SF4 mRNA and protein levels were highly expressed in tumor specimens of HCC patients as compared to non-tumor tissues, with more abundant in the plasma membrane and less in the cytoplasm and none in the nucleus." (PMID 36678607, 2023). "However, in the stromal cells of the tumor buds, LGALS1 was downregulated and candidate genes SERPINB5 and TM4SF4 were upregulated, as compared with the control." (PMID 28687755, 2017). "Moreover, according to Huang, Wang, TM4SF4 may affect colorectal cancer (CRC) cells’ metastatic behavior, where its overexpression and S100B and OLFM4 genes have been found in the circulating tumor cells of blood specimens of 103 preoperative CRC patients." (PMID 36678607, 2023).
tumor (continued). "TM4SF4 and TM4SF5 in the L6 family are also involved in tumor regulation, but their exact mechanism is not yet known." (PMID 36209368, 2022).
infection (1 paper, 2015). The state of being infected such as from the introduction of a foreign agent such as serum, vaccine, antigenic substance or organism. "In addition to immunity, genes associated with metabolism (e.g. SLC5A6, SLC2A5, UGT2A3, and PDE6C) as well as membrane proteins, like TM4SF4, were also detected with a significantly higher expression level in CE infection sheep at four hour post infection, when compared with healthy controls." (PMID 26252489, 2015).
TM4SF4 also shares sentences with these, for which no sentence is quoted: adenocarcinoma (2 papers); cholangiocarcinoma (1); cholelithiasis (1); Cirrhosis (1); colorectal cancer (1); liver diseases (1); non-small cell lung carcinoma (1); ovarian carcinoma (1).